PRAME (PRAME nuclear receptor transcriptional regulator)
Diseases named in the same sentence as PRAME in open-access papers (continued):
Sharing a sentence is not in itself a finding about the gene and the disease.
ovarian carcinoma (19 papers, 2004 to 2025). A malignant neoplasm originating from the surface ovarian epithelium. "Aside from that, CCT4 up-regulation and PRAME mutations was correlated with a good prognosis for ovarian cancer patients." (PMID 37835834, 2023). "The CCT4 up-regulation and PRAME mutations were correlated with a good prognosis for ovarian cancer, while higher levels of GAGE2A and CT45A1 mRNAs were correlated with a poor prognosis for ovarian cancer patients." (PMID 37835834, 2023). "One of the mutations in the PRAME gene that correlated with survivability of ovarian cancer patients was the functionally significant Ala99Ser mutation." (PMID 37835834, 2023). "Notably, a study has analyzed 21 ovarian cancer‐associated CTAs and found that GAGE2, CT45, CCT4, and PRAME cancer/testis antigens were revealed to be correlated with the prognosis for ovarian cancer patients." (PMID 38896069, 2024). "Targeting TCRs against the cancer assessment antigens NY-ESO1, MAGE-A4, and PRAME has been studied in clinical trials in patients with ovarian cancer." (PMID 39253578, 2024). "PRAME has emerged as a significant tumor-specific antigen for ovarian cancer therapy, particularly in high-grade serous carcinoma (HGSC)." (PMID 39033780, 2024). "Identified for its high expression relative to healthy tissues, PRAME’s promoter hypomethylation correlates with increased mRNA levels across various stages and grades of ovarian cancer." (PMID 39033780, 2024). "Previously, high expressions of MAGEA4 and PIWIL1 were found in epithelial ovarian cancer; furthermore, the expression of PRAME was found in ovarian, uterine, and other tumor types." (PMID 37835834, 2023). "We have previously reported on the expression of MAGE-A3, MAGE-A4, MAGE-A10, and PRAME in a subset of these ovarian cancers." (PMID 35158998, 2022). "By contrast, the role of PRAME in breast and ovarian cancers is less well defined, though emerging evidence suggests it may correlate with adverse prognosis in these settings as well." (PMID 40868240, 2025). "In contrast, PRAME expression in breast and ovarian cancers is less well characterised, but preliminary studies suggest that it may also be associated with a worse prognosis." (PMID 38338862, 2024). "Thus, GAGE2, CT45, CCT4, and PRAME cancer/testis antigens can be considered as new potential prognostic markers for ovarian cancer disease and need to be further investigated." (PMID 37835834, 2023). "Our results demonstrated that PRAME upregulation is triggered by direct binding of SS18-SSX to the PRAME promoter, in line with a previous report on SS18 in ovarian cancer." (PMID 39550391, 2024). "In clinical trials with ovarian cancer patients, TCRs targeting cancer-testis antigens (CTAs) NY-ESO-1, MAGE-A4 and more recently PRAME have been investigated." (PMID 37026005, 2023). "In this study, we describe the selection of PRAME, CTCFL and CLDN6 as strictly tumor-specific targets for patients with ovarian cancer." (PMID 37026005, 2023). "The identified PRAME and CTCFL TCRs are promising candidates for the treatment of patients with ovarian cancer, and are an essential addition to the currently used HLA-A*02:01 restricted PRAME TCRs." (PMID 37026005, 2023). "Among the 21 selected CTAs, GAGE2, CT45, CCT4, and PRAME cancer/testis antigens were revealed to be correlated with the prognosis for ovarian cancer patients, and GAGE2, CCT4, and PRAME were identified for the first time." (PMID 37835834, 2023). "By performing a differential gene expression analysis using mRNA-seq datasets, PRAME, CTCFL and CLDN6 were selected as strictly tumor-specific TAAs, with high expression in ovarian cancer and at least 20-fold lower expression in all healthy tissues of risk." (PMID 37026005, 2023). "In summary, our study reveals that PRAME is frequently expressed in EOC and HGSC, and establishes it as a potential candidate for immunotherapy in ovarian cancer." (PMID 27322684, 2016).
ovarian carcinoma (continued). "We confirmed a number of ovarian cancer genes previously identified by GEM, for example, CD24, HE4, PRAME, B-factor (properdin), and, where our studies overlap, the data are highly consistent, despite the difference in methodology." (PMID 14760385, 2004). "Amerongen72 and colleagues found that the PRAME and CTCFL TCR‐T cells demonstrated potent and specific antitumor reactivity both in vitro and in vivo, the identified PRAME and CTCFL TCRs are promising candidates for the treatment of patients with ovarian cancer." (PMID 38896069, 2024). "The members of the CTA family in ovarian cancer mainly include MAGE, GAGE 1/2, LAGE‐1, NY‐ESO‐1, SSX, CT45, and TRAG‐3, which belong to the CT‐X antigen, and AKAP3/4, BAGE, BORIS, OY‐TES‐1(CT23), PRAME, PIWIL, HSP70‐2, SPAG9, and SP17, which belong to non‐X CT antigen." (PMID 38896069, 2024). "By combining mRNA-seq datasets of healthy and tumor tissues, we selected preferentially expressed antigen of melanoma (PRAME), CCCTC-binding factor (CTCFL), and Claudin-6 (CLDN6) as TAAs with high expression in ovarian cancer and at least 20-fold lower expression in all healthy tissues of risk." (PMID 37026005, 2023). "Thus, GAGE2, CT45, CCT4, and PRAME cancer/testis antigens can be considered as potential prognostic markers for ovarian tumors, and GAGE2, CCT4, and PRAME were revealed to be correlated with the prognosis for ovarian cancer patients for the first time." (PMID 37835834, 2023). "A large number of putative suppressor genes that are silenced or activated by aberrant methylation have been identified in ovarian cancer, including hypermethylation of OPCML, RASSF1, CDKN2B as well as classical tumor suppressors BRCA1, p16 and MLH1, and hypomethylation of LINE-1, SLC6A12 and PRAME." (PMID 35710397, 2022). "PRAME is a cancer-testis antigen (CTA) and potential immuno-therapeutic target, but has not been well-studied in epithelial ovarian cancer (EOC) or its high grade serous (HGSC) subtype." (PMID 27322684, 2016).
sarcoma (17 papers, 2008 to 2026). A usually aggressive malignant neoplasm of the soft tissue or bone. "Also, elevated PRAME expression in sarcomas has been associated with adverse clinical features, including larger tumor size, the presence of necrosis, and higher histological grade." (PMID 40868240, 2025). "The probability of PRAME expression was the highest (21.88%) in all the sarcoma samples we examined." (PMID 40152485, 2025). "The expression of MAGE‐A4 and PRAME in these sarcomas was significantly different from that in references." (PMID 40152485, 2025). "The initial workup of this undifferentiated tumor demonstrated strong PRAME immunopositivity in a tumor ultimately deemed to be a CIC::DUX4 sarcoma via whole transcriptome exome sequencing." (PMID 40599504, 2025). "PRAME is a cancer–testis antigen that is expressed in the normal testis and several sarcoma subtypes, such as synovial sarcoma, multifocal leiomyosarcoma, myxoid/round cell liposarcoma, and osteosarcoma." (PMID 38256198, 2024). "The malignant cells expressed the characteristic markers for FDC sarcoma but with positivity of the melanocytic marker PRAME." (PMID 39379758, 2024). "The efficacy of action on sarcoma cells, determined by CI change, correlated with the presence of expression of the gene PRAME (rho = 0.713, adj." (PMID 32042403, 2020). "Significant PRAME overexpression has been described in uterine carcinosarcoma, synovial sarcoma, and multifocal leiomyosarcoma, while other sarcoma subtypes appear to express PRAME less frequently." (PMID 33287125, 2020). "Several CTAs, like MAGE, NY-ESO-1, and PRAME, are expressed in different sarcoma subtypes, such as synovial sarcoma, myxoid/round cell liposarcoma, and other soft tissues sarcomas." (PMID 33287125, 2020). "Analyzing the expression of PRAME in sarcoma subtypes, we found that PRAME was highly expressed in all synovial sarcomas." (PMID 28630682, 2017). "Expression of PRAME in the uterine carcinosarcoma TCGA (n = 57) was significantly higher (p < 0.001) compared to the sarcoma TCGA as a whole, and only skin cutaneous melanoma showed a higher PRAME expression among all normal and tumor tissue types." (PMID 28630682, 2017). "Although the other sarcoma tumors included in the sarcoma TCGA showed a lower expression, a subset of samples was clearly characterized by PRAME overexpression." (PMID 28630682, 2017). "To determine the relevance of PRAME as a target in sarcoma, we compared all normal (GTEx, n = 30 tissue types, n = 8153 samples) and tumor tissue (TCGA, n = 33 cancers) expressions." (PMID 28630682, 2017). "Multiple CCLE cell lines that were derived from sarcoma tumors retained PRAME expression, with the exception of chondrosarcoma, which was not included in the sarcoma TCGA." (PMID 28630682, 2017). "The goal of this study is to evaluate the expression of PRAME across multiple sarcoma subtypes and normal tissues using three large public datasets." (PMID 28630682, 2017). "These factors contribute to a poorer prognosis, suggesting that PRAME could serve as a prognostic biomarker in certain sarcoma subtypes." (PMID 40868240, 2025). "Moreover, in our mixed cohort of intermediate and high-grade sarcomas, PRAME expression was prognostic for unfavourable survival, which was not the case in the studies of liposarcoma, leiomyosarcoma, and synovial sarcoma subgroups by others." (PMID 33287125, 2020). "In the current study, we show that PRAME could be an effective immunotherapy target in specific sarcoma subtypes." (PMID 28630682, 2017). "Notably, all other sarcoma subtypes showed a highly heterogeneous PRAME expression, from zero to very high expression." (PMID 28630682, 2017). "PRAME, like other cancer-testis antigens, has been shown be minimally expressed in adult human organs except for gonadal tissues and various human cancers including sarcomas." (PMID 28630682, 2017).
sarcoma (continued). "To map the landscape of PRAME expression in sarcoma, we used publicly available data from The Cancer Genome Atlas (TCGA) and the Cancer Cell Line Encyclopedia (CCLE) projects and determined which sarcoma subtypes and subsets are associated with increased PRAME expression." (PMID 28630682, 2017). "The poly‐expression of MAGE‐A4, PRAME, and MAGE‐A1 across all subtypes suggests that these antigens may serve as potential targets for sarcoma‐specific immunotherapy." (PMID 40152485, 2025). "For example, PRAME, CTAG1, and CTAG2 have been reported to be over-expressed in liposarcoma compared with a variety of normal tissues, and recent studies have reported the expression of these and other CTAGs in several sarcoma subtypes." (PMID 18460215, 2008). "To date, PRAME immunopositivity has not been reported in CIC-rearranged sarcomas." (PMID 40599504, 2025). "Interestingly, expression of CTAG1B/A and PRAME has recently been correlated with tumor grade and poor prognosis in myxoid sarcomas, supporting our hypothesis that CTAG1B/A is active in sarcoma biology." (PMID 35664317, 2022). "Interestingly, the sarcoma demonstrated very strong PRAME immunohistochemical positivity, a diagnostic finding that has not yet been reported on CIC::DUX4 sarcomas and has potential use as a beneficial tool in the workup of a diagnostically challenging disease." (PMID 40599504, 2025).
cutaneous melanoma (15 papers, 2012 to 2025). A primary melanoma arising from atypical melanocytes in the skin. "Its aberrant overexpression in various malignancies, particularly cutaneous melanoma, is associated with more aggressive tumour phenotypes, positioning PRAME as both a diagnostic and prognostic marker." (PMID 38338862, 2024). "However, research in this field is rapidly evolving, and markers such as PRAME have emerged as promising candidates for diagnostic, prognostic, and even therapeutic use in cutaneous melanoma." (PMID 41155720, 2025). "A separate investigation using immunocytochemical methods reported PRAME positivity in 85.4% of cutaneous melanoma metastases." (PMID 40868240, 2025). "PRAME was broadly expressed across cutaneous melanoma and lung tumors with distinct TMB and PD-L1 biomarker profiles, with some enrichment in NSCLC adenocarcinomas with higher TMB and lower PD-L1 levels." (PMID 39659431, 2024). "In the phase 1 clinical trials of brenetafusp (IMC-F106C), an ImmTAC bispecific molecule targeting PRAME, for patients with late-line, immune checkpoint pre-treated cutaneous melanoma, the treatment demonstrated promising disease control." (PMID 39451258, 2024). "To further confirm the specificity of the PRAME-targeting ImmTAC® molecule, we deleted the target peptide sequence (SLLQHLIGL) in a cutaneous melanoma cell line that expresses abundant PRAME peptide in the context of HLA-A*02:01 (MEL624)." (PMID 39659431, 2024). "In line with previous studies, PRAME expression was detected in multiple highly prevalent primary tumors, with frequencies >90% in skin cutaneous melanoma (SKCM), and ≥75% in endometrial, ovarian, NSCLC) SCC, and small cell lung cancer (SCLC)." (PMID 39659431, 2024). "We confirm that PRAME protein is expressed in cutaneous melanoma, including rare subtypes with limited treatment options, as well as primary and metastatic lung, breast, endometrial, and ovarian tumors." (PMID 39659431, 2024). "Further studies are needed to determine the prognostic value of PRAME expression in cutaneous melanoma, regarding the role of PRAME in the relationship between immune response and oncogenesis." (PMID 35484605, 2022). "While PRAME expression has been linked to a negative prognostic in uveal and mucosal melanomas, this association has not been established for cutaneous melanomas." (PMID 41155720, 2025). "Metastases of primary cutaneous melanomas also exhibit PRAME expression." (PMID 40507250, 2025). "As we gain a better understanding of how targeting PRAME can enhance T cell-mediated tumor destruction, it may become a pivotal approach in treating cutaneous melanoma and possibly other cancers with high PRAME expression." (PMID 39857682, 2025). "In addition, current studies are focusing on developing additional targets for bispecific antibodies in the treatment of cutaneous melanoma, such as PRAME." (PMID 39204391, 2024). "PRAME positivity was observed in 85.4% of 48 cutaneous melanoma metastases." (PMID 39451258, 2024). "T cell engagers targeting PRAME are presently undergoing extensive evaluation in large phase 1 and 2 clinical trials for all recurrent or refractory PRAME-positive solid tumors, encompassing cutaneous melanoma (NCT05958121 and NCT04262466)." (PMID 39204391, 2024). "Additionally, we demonstrate that PRAME is expressed in cutaneous melanoma specimens that are refractory to immune checkpoint blockade." (PMID 39659431, 2024). "PRAME expression was also detected at high frequency in acral and mucosal cutaneous melanoma, rare subtypes that are biologically and clinically distinct from cutaneous melanoma, with limited therapeutic options." (PMID 39659431, 2024). "Similarly, a sample of 155 primary cutaneous melanomas, excluding desmoplastic melanomas, showed PRAME positivity in 92% of the cases." (PMID 39451258, 2024).
cutaneous melanoma (continued). "Unlike previous studies, we assessed the expression of PRAME using only subungual melanocytic lesions, known to have different genomic alterations with lower mutation burden compared with other cutaneous melanomas." (PMID 35484605, 2022). "However, it is striking that all subsequent studies from other groups, including ours, described lower PRAME expression in cutaneous melanomas." (PMID 34359765, 2021). "Furthermore, we are exploring the potential of T cell engagers directed against the cancer testis antigen PRAME, which could have widespread utility in the treatment of cutaneous melanoma as well as other PRAME-expressing malignancies." (PMID 39204391, 2024). "Immunohistochemistry-based biomarkers including PRAME, Ki-67, AMBLor, YB-1, TRPM1, and MITF have been investigated as prognostic markers in cutaneous melanoma." (PMID 40981345, 2025). "The expression of PRAME in 88% of primary cutaneous melanomas and lack of expression in normal nevi make it particularly useful." (PMID 23209909, 2012). "Also, it has been reported that primary cutaneous melanoma could be completely negative for PRAME immunostaining." (PMID 35484605, 2022).
lung carcinoma (13 papers, 2016 to 2025). "PRAME was homogenously expressed across all skin, endometrial, ovarian, breast, and lung cancer types tested, suggesting that a PRAME-targeted therapy has the potential to act on most malignant cells within the tumor microenvironment." (PMID 39659431, 2024). "PRAME was also found to be involved in the progression of liver cancer and lung cancer through cell cycle regulation via the degradation of p14/ARF." (PMID 36980687, 2023). "Taken together, these data clearly demonstrate that PRAME play important roles in lung cancer development." (PMID 27391090, 2016). "In consistent with these studies, a previous study has shown that PRAME is also expressed in lung cancers." (PMID 27391090, 2016). "In supporting the role of PRAME in lung cancer metastasis, we demonstrated that decrease the expression of PRAME dramatically increased the proliferation of lung cancer cells PC9 and A549." (PMID 27391090, 2016). "In line with the protection of PRAME in lung cancer, our data showed that knockdown of PRAME increased the invasion of lung cancer cells." (PMID 27391090, 2016). "After the knockdown of PRAME, the proliferation of both PC9 and A549 cells was significantly increased starting at 3 days after transfection as evidenced by MTT assay, suggesting that PRAME inhibits lung cancer cell proliferation." (PMID 27391090, 2016). "Knockdown of PRAME decreases the expression of E-Cadherin and promotes the proliferation, invasion, and metastasis of lung cancer cells by regulating multiple critical genes, most of which are related to cell migration, including MMP1, CCL2, CTGF, and PLAU." (PMID 27391090, 2016). "To investigate the role of PRAME in lung cancer cell progression, we examined the effect of PRAME knockdown on lung cancer cell proliferation and invasion." (PMID 27391090, 2016). "Downregulation of PRAME in lung cancer cells promotes the metastasis via E-cadherin signaling pathway." (PMID 27391090, 2016). "The number of cells penetrated through the Matrigel was dramatically increased in both PC9 and A549 cells when transfected with PRAME siRNA, indicating that PRAME inhibits the invasion of lung cancer cells." (PMID 27391090, 2016). "The mRNA and protein expressions of both PRAME and E-cadherin were down regulated in lung cancer and lung bone metastasis compared with that in normal lung tissue." (PMID 27391090, 2016). "Notably, the downregulation of PRAME significantly impedes cancer cell growth by inducing G2/M cell cycle arrest in hepatocellular carcinoma cell lines and lung cancer cell lines." (PMID 38132219, 2023). "Drugs promoting the expression of PRAME could be developed to prevent the progression and metastasis of lung cancer." (PMID 27391090, 2016). "Moreover, knockdown of PRAME decreased the expression of E-cadherin and promoted the proliferation of lung cancer cells PC9 and A549." (PMID 27391090, 2016). "However, the functional roles of PRAME in lung cancer development remain largely unrevealed." (PMID 27391090, 2016). "To further examine the role of PRAME on lung cancer cell development, we performed RNA-seq analysis in PC9 cells transfected with control or PRAME siRNA." (PMID 27391090, 2016). "Combined our PPI network analysis with previous studies, PRAME knockdwon upregulates MMP1, CCL2, CTGF, and PLAU and contribute to lung cancer metastasis." (PMID 27391090, 2016).